SMO (smoothened, frizzled class receptor)
Diseases named in the same sentence as SMO in open-access papers (continued):
Sharing a sentence is not in itself a finding about the gene and the disease.
medulloblastoma (continued). "Analysis of GLI1 protein expression in SUFU-positive and SUFU-deficient human medulloblastoma cells and Sufu knockout mouse embryonic fibroblasts further corroborated the potent activity of DYRKi to inhibit GLI activity in SMO-inhibitor sensitive and resistant cells." (PMID 26784250, 2016). "In a smoothened (SMO)-activated medulloblastoma model, MB-FUS delivery of SMO-targeted siRNA significantly reduced the production of SMO protein and promoted tumor-cell death." (PMID 37416764, 2023). "Not only that, but also the crosstalk between SHH and other oncogenic pathways that are commonly overactivated in medulloblastoma, such as PI3K/mTOR and RAS/REF/MEK, can play a significant role in evading SMO inhibition." (PMID 37568705, 2023). "Intriguingly, the co-inhibition of CXCR4 and SMO using AMD3100 and vismodegib, respectively, attenuated the proliferation of SHH-driven medulloblastoma flank and intracerebellar xenografts." (PMID 37568705, 2023). "The SMO inhibitors vismodegib/GDC-0449 and sonidegib/LDE225 are currently being evaluated for treating SHH medulloblastomas." (PMID 36688010, 2022). "The mPEG5kDa-cholane/GlaB micellar system can be properly exploited in the treatment of patients with medulloblastoma, particularly for those tumors showing resistance to SMO inhibitors or harboring GLI1 hyperactivation by SMO-independent mechanisms." (PMID 35163655, 2022). "Herein, we have assessed transcriptomic public records of two microarray datasets and found that YAP1 is explicitly overexpressed in patients profiled as poor responders to SMO inhibitors (e.g., Sonidegib, Vismodegib) and in SHH medulloblastoma subtype alpha." (PMID 34944872, 2021). "For instance, PI3K/MTOR inhibition can delay therapeutic resistance against SMO inhibitors in mouse models of cancer, including BKM120 cotreatment in HH-driven medulloblastoma or cotreatment with the MTOR inhibitor RAD-001 in esophageal adenocarcinoma." (PMID 34268113, 2021). "SHH-activated medulloblastoma is highly heterogeneous and many key molecules in the SHH signaling pathway such as SUFU, smoothened (SMO), PTCH1, GLI1 and GLI2 have been dysregulated in this subgroup." (PMID 33869004, 2021). "To date, the majority of pediatric brain tumor GEMMs are SHH-activated medulloblastoma, which are generated by modifying SHH signaling genes, such as PTCH, SMO, or SUFU." (PMID 33869004, 2021). "The recently published MEVITEM trial evaluated vismodegib, another SMO inhibitor, plus temozolomide in immunohistochemically defined, recurrent, SHH-driven adult medulloblastoma." (PMID 34298664, 2021). "Specifically, IBET-151 attenuates HH signaling in cells with constitutive GLI1 activity in a SMO-independent fashion in BCC, medulloblastoma, and atypical teratoid/rhabdoid tumor." (PMID 32913560, 2020). "Initial studies in medulloblastoma and BCC suggest that vismodegib resistance stems from genetic alterations at the level of or downstream from SMO." (PMID 32913560, 2020). "Dysregulation of the seven-transmembrane (7TM) receptor Smoothened (SMO) and other components of the Hedgehog (Hh) signaling pathway contributes to the development of cancers including basal cell carcinoma (BCC) and medulloblastoma (MB)." (PMID 31539380, 2019). "While the efficacy of SMO inhibitors in BCC and medulloblastoma is satisfactory, clinical trials in other solid cancers including colorectal, pancreatic, or lung cancer were disappointing." (PMID 31027259, 2019). "For example in a mouse model of medulloblastoma, addition of PI3K inhibitor BKM120 or PI3K/mTOR inhibitor BEZ235 to the initial treatment with SMO inhibitor LDE225 markedly delayed the occurrence of resistance." (PMID 25749378, 2015). "In other words, mice with wild-type cilia and active SMO produced medulloblastomas and BCCs, whereas mice with mutant cilia and active SMO did not develop tumours." (PMID 39234399, 2024).
medulloblastoma (continued). "However, Hh pathway components, particularly GLI1, are ideal predictive biomarkers for SMO inhibitor therapy in several cancers, including BCC and Shh-medulloblastomas." (PMID 34572373, 2021). "Indeed, vismodegib, a SMO-specific inhibitor, is a promising therapeutic approach for cancer treatment in BCC and medulloblastoma, but the effectiveness remains to be determined in GBM." (PMID 33446260, 2021). "Failure of SMO inhibitors in these malignancies can be at least partly explained in that aberrant Hh signaling in these cancers, unlike medulloblastoma or BCC, is not driven by mutational mechanisms effectively targeted by SMO inhibition." (PMID 27539549, 2016). "The lack of efficacy of SMO inhibitors and the acquired resistance to these inhibitors in medulloblastoma patients argues for the use of GLI-specific inhibitors." (PMID 27519263, 2016). "In clinical trials, SMO inhibitors have now been demonstrated to have potent antitumor activity in patients with BCC and one patient with medulloblastoma, thus confirming an “oncogene addiction” model in which deregulated Hh signaling results in increased cell proliferation and tumor formation." (PMID 21188169, 2011). "According to a study on medulloblastoma, non-ciliated cells, even those with constitutively active SMO, could not develop tumours, whereas ciliated precursor cells lacking PTCH1 were capable of developing tumours." (PMID 39234399, 2024). "In the same token, the Hh antagonist Vismodegib, a cyclopamine derivative that binds SMO preventing Gli activation and macrophage recruitment modifier, is a clinically approved therapy to treat BCC and is undergoing phase II clinical trials for medulloblastoma and other cancers [NCT00833417]." (PMID 37305676, 2023). "The search for small molecules that might act upstream of the GPR56‐associated network led us to the CDK7/12/13 inhibitor THZ1, as it had been shown to overcome resistance to SMO antagonists in medulloblastoma by acting upstream and independent of SMO." (PMID 35253392, 2022). "Indeed, the SMO inhibitors Vismodegib and Sonidegib are FDA-approved to treat SMO hyperactivity in BCC and have shown promising efficacy in SHH-dependent preclinical models of medulloblastoma and others." (PMID 32957513, 2020). "Furthermore, mutation of the putative miR-324-5p complementary seed sites within both the GLI1 and SMO 3′UTRs prevented miR-324-5p from exerting its repressive effects on the constructs, confirming miR-324-5p acts directly on the human SMO and GLI1 3′UTR, as proposed in medulloblastoma." (PMID 30193893, 2019). "Furthermore, we identified overexpression of GLI2 and SMO as a signature of resistance to smoothened inhibition in melanoma, as has been reported recently in human medulloblastoma using both NVP-LDE-225 and Vismodegib, an oral SMO inhibitor that is FDA-approved in advanced basal cell carcinoma." (PMID 24287465, 2013). "Sonidegib is a potent oral SMO inhibitor, which showed efficacy in patients with solid tumors and was evaluated in a phase II (ClinicalTrials.gov: NCT01125800, 26 May 2020) and a phase III trial (ClinicalTrials.gov: NCT01708174, 26 May 2020) in pediatric and adult patients with medulloblastoma." (PMID 34298664, 2021). "A large majority of sporadic medulloblastomas and basal cell carcinomas also exhibit hyperactive Hh signaling (in a ligand-independent fashion) due to mutations in Hh pathway components including, PTCH, SMO, and occasionally Suppressor of Fused (SUFU), a negative regulator of the Hh pathway." (PMID 21188169, 2011). "(b) Ligand-independent model: Clinical observations have found mutations of PTCH-1 and PTCH-2 in basal cell carcinomas and in medulloblastomas, resulting in dysregulated GLI signaling due to ineffective sequestration of SMO signaling, regardless of SHh ligand levels." (PMID 34113570, 2021).
medulloblastoma (continued). "Furthermore, SMO-independent noncanonical signaling can also influence proliferation and cell cycle regulation in some cell types, notably cerebellar granule precursor cells, which may give rise to medulloblastoma through GLI1-mediated induction of n-myc and Cyclin D1." (PMID 32957513, 2020). "Clinical trials based on the administration of SMO antagonists have demonstrated effectiveness in HH-driven tumors, such as BCC and medulloblastoma; however, the therapeutic efficacy of SMO inhibitors may not be effective in tumors having non-canonical activation of GLI1." (PMID 33958721, 2021).
basal cell carcinoma (114 papers, 2012 to 2025). A carcinoma involving the basal cells. "Despite mounting evidence of an SMO‐independent variant Hh route, SMO inhibitors have evolved to treat basal cell carcinoma." (PMID 40969301, 2025). "In about 50% of resistant basal cell carcinomas (BCCs), SMO mutations maintain HH pathway activation despite inhibitor treatment." (PMID 39568072, 2024). "Mutation or abnormal expression of SMO or Hh genes can lead to cell-specific proliferation, and involvement in tumor development, with basal cell carcinoma, lung cancer, or breast cancer, is closely related." (PMID 37139482, 2023). "Inactivating mutations of PTCH1 and SMO, occur in 90% and 10%, respectively of basal cell carcinoma." (PMID 37013122, 2023). "Inactivating mutations in PTCH1 and activating mutations in SMO have been detected in 73% or 20%, respectively, of patients with basal cell carcinoma (BCC), a stem cell-based malignancy accounting for ~90% of all solid tumors." (PMID 34518642, 2021). "Whole exome sequencing of vismodegib resistant basal cell carcinomas from patients with Gorlin syndrome, an autosomal dominant disease that causes early onset basal cell carcinoma, identified several mutations in SMO." (PMID 32283832, 2020). "Previous studies have demonstrated that loss of function mutations of the tumor suppressor PTCH1 or gain of function mutations of SMO are associated with basal cell carcinoma." (PMID 32784501, 2020). "Hh pathway mutations like PTCH1 are known to be oncogenic in basal cell carcinoma and have been successfully targeted with small molecule inhibitors of smoothened (SMO) like vismodegib." (PMID 31394751, 2019). "Somatic mutations in the components of Hh signaling (PTCH1 and SMO) have been shown to be a major cause of basal cell carcinoma, and dozens of Hh inhibitors have been developed." (PMID 31775795, 2019). "Somatic mutations of PTCH1 and SMO were identified in patients with basal cell carcinoma and medulloblastoma." (PMID 28105432, 2016). "Vismodegib, an inhibitor of SMO oncoprotein, caused regression of basal-cell carcinomas in patients with Gorlin syndrome." (PMID 23548133, 2013). "In basal cell carcinoma, PC loss could inhibit tumor growth induced by the activated form of the SMO upstream activator." (PMID 37101292, 2023). "The PTCH and SMO genes are frequently mutated in basal cell carcinomas and neuroblastomas." (PMID 33966040, 2021). "SMO mutations causing secondary resistance to SMO inhibitors are reported in basal cell carcinoma." (PMID 31394751, 2019). "In conclusion, selected SMO antagonist-resistant metastatic basal cell carcinomas may respond to nivolumab based on underlying molecular genetic mechanisms that include PD-L1 amplification and high tumour mutational burden." (PMID 27942391, 2016). "Another example is the use of SMO antagonists, which block Hh signaling in basal cell carcinoma and other cancers." (PMID 40969301, 2025). "Vismodegib (VSM), approved for treating advanced basal cell carcinoma, inhibits the hedgehog pathway by targeting the smoothened receptor (SMO)." (PMID 40240356, 2025). "Clinical trials based on the administration of small molecule inhibitors targeting SMO have demonstrated effectiveness in HH-driven tumors, such as advanced basal cell carcinoma." (PMID 39998753, 2025). "Vismodegib, a hedgehog (Hh) pathway inhibitor, is used to treat locally advanced or metastatic basal cell carcinoma (BCC) by blocking the activity of smoothened homolog (SMO), a key protein in the Hh pathway." (PMID 40334012, 2025). "For example, Vismodegib (Vis) and sonidegib are Food and Drug Administration (FDA)-approved oral small-molecule SMO inhibitors used in the treatment of metastatic basal cell carcinoma." (PMID 40426308, 2025). "For example, in basal cell carcinoma, nuclear localisation of SMO via a nuclear/nucleolar localisation signal activates GLI1 independently of canonical SMO inhibitors, explaining resistance in ~80% of patients." (PMID 40426308, 2025).
basal cell carcinoma (continued). "Preclinical studies indicate that inhibiting SMO can prompt the shift of basal cell carcinoma to squamous cell carcinoma by promoting c-FOS activation of the EGFR/RAS/MAPK pathway." (PMID 38067165, 2023). "LDE225 (also known as Erismodegib/Sonidegib) is a SMO inhibitor as evidenced in vitro and in vivo as a SMO antagonist, and is currently marketed as Odomzo® to treat advanced stage basal cell carcinoma (BCC) [NCT04066504]." (PMID 37305676, 2023). "Among potential JNK3 inhibitors identified by structure-based virtual screening, sonidegib, an SMO antagonist approved for the treatment of basal cell carcinoma, was selected for further investigation." (PMID 36142500, 2022). "As the second SMO antagonist, sonidegib was approved in 2015 for the treatment of advanced basal cell carcinoma." (PMID 36142500, 2022). "Among the drugs screened, sonidegib, a selective smoothened (SMO) antagonist approved for the treatment of advanced basal cell carcinoma, is one of the potential JNK3 inhibitors." (PMID 36142500, 2022). "Dysfunctional PTCH1 causes constitutive activation of smoothened (SMO), resulting in continuous activation of hedgehog signaling and its target genes in basal cell carcinoma, making SMO a promising target." (PMID 36209184, 2022). "The small molecule inhibitors vismodegib and sonidegib are FDA/EMA approved SMO antagonists used to treat advanced basal cell carcinoma and other cancers." (PMID 34576017, 2021). "Remarkable efficacy of anti-HH therapeutics led to the approval of HH inhibitors targeting the key pathway effector smoothened (SMO) in basal cell carcinoma and acute myeloid leukemia." (PMID 34439381, 2021). "At present, two Hedgehog pathway-targeted drugs that act on SMO protein, Vimodji and Songyib, have been approved for clinical treatment of basal cell carcinoma." (PMID 34692546, 2021). "Fas expression is low in human and murine basal cell carcinomas but is upregulated in the presence of the SMO antagonist, cyclopamine, both in vitro as in vivo." (PMID 34445078, 2021). "The first inhibitors of oncogenic HH—GLI that were approved by the FDA for the treatment of advanced and metastatic basal cell carcinoma (BCC) were the small molecule SMO inhibitors (SMOi), vismodegib and sonidegib." (PMID 34439381, 2021). "As reported in basal cell carcinoma (BCC), tumor cells would frequently acquire resistance to Vismodegib, with multiple SMO mutations." (PMID 32723329, 2020). "Basal cell carcinomas (BCCs) depend on Hedgehog (Hh)/Gli signaling, but can develop mechanisms of Smoothened (SMO) inhibitor resistance." (PMID 33033234, 2020). "FDA-approved SMO (Smoothened) inhibitor- Vismodegib binds directly to SMO and inhibits the progression of advanced basal cell cancers." (PMID 31921137, 2019). "In sporadic basal cell carcinomas, approximately 70% of cases present a mutation of Shh pathway-related genes (inactivating mutation of PTCH or activating mutation of SMO)." (PMID 29581874, 2018). "In the case of basal cell carcinoma (BCC), Hh dysregulation is driven by a mutations in the PTCH1 gene, which blocks its ability to repress SMO." (PMID 30379908, 2018). "The SMO inhibitor Vismodegib (GDC-0449/Erivedge) has been approved for treatment of basal cell carcinoma." (PMID 29396391, 2018). "Inhibitors targeting the Hh signal transducer Smoothened (SMO) are widely used and display a good initial efficacy in patients suffering from basal cell carcinoma (BCC); however, a large number of patients relapse." (PMID 29695137, 2018). "Conditional deletion of KIF3A or IFT88 in basal cell carcinoma leads to ciliary elimination and strong inhibition of tumorigenesis induced by mutant SMO." (PMID 27793025, 2016). "In basal-cell carcinoma, where over 90% of tumors have mutations in either SMO or PTCH, SMO inhibition has been particularly effective in the setting of locally advanced and metastatic disease." (PMID 27458586, 2016).